POFUT1 (protein O-fucosyltransferase 1)
Diseases named in the same sentence as POFUT1 in open-access papers (continued):
Sharing a sentence is not in itself a finding about the gene and the disease.
adenoma (2 papers, 2020). A neoplasm arising from the epithelium. "POFUT1 was recently shown to exert an essential role in the colorectal progression from precancerous lesions (adenomas) to carcinoma." (PMID 32486426, 2020). "High expression of POFUT1 in HRAs and CRCs was validated using immunohistochemical staining of TMAs and adenoma‐derived organoids." (PMID 31411736, 2020). "Altogether this suggests that POFUT1 through the Notch signaling pathway is a putative driver of adenoma‐to‐carcinoma progression." (PMID 31411736, 2020). "POFUT1, RPRD1B and EIF6 were identified as putative drivers of adenoma‐to‐carcinoma progression." (PMID 31411736, 2020).
colon cancer (2 papers, 2018 to 2025). "Furthermore, in vivo metastasis experiments in mice, where colon cancer cell lines with high and low POFUT1 expression were injected, demonstrated that cells with high POFUT1 expression promoted metastatic nodules in the liver, confirming its role in enhancing invasion." (PMID 40773107, 2025). "It was found that POFUT1 is elevated in colon cancer cells compared to normal colon epithelial cell line and normal colon tissues, which further implicating its contribution to CRC pathogenesis." (PMID 30250219, 2018).
colorectal adenoma (2 papers, 2020 to 2021). An adenoma that arises from the colon or rectum. "POFUT1 expression was associated with Notch signaling and decreased goblet cell differentiation and was identified as a potential driver of tumor progression in colorectal adenomas." (PMID 34510716, 2021). "In‐depth molecular characterization of colorectal adenomas revealed POFUT1 and Notch signaling as potential drivers of tumor progression." (PMID 31411736, 2020). "POFUT1 overexpression was successfully validated by immunohistochemical staining on TMAs and in patient‐derived colorectal adenoma organoids, indicating that POFUT1 plays a role in colorectal adenoma‐to‐carcinoma progression." (PMID 31411736, 2020).
colorectal tumor (2 papers, 2018 to 2020). "Lower amounts of goblet cells were significantly associated with high POFUT1 expression (p = 0.017) and high risk of progression (p = 0.007), implying that also in our study POFUT1 is linked to goblet cell differentiation and indicating its role in early colorectal tumor development." (PMID 31411736, 2020). "Also in the organoids, POFUT1 was mainly observed in the cytoplasm and high POFUT1 expression was associated with HRAs (p = 0.008), confirming its potential role in early colorectal tumor development." (PMID 31411736, 2020). "In parallel, based on six different colorectal tumors, we detected POFUT1 and estimated the number of POFUT1 copies." (PMID 30380753, 2018). "Moreover, the findings highlight POFUT1 and Notch signaling as potential drivers of colorectal tumor development." (PMID 31411736, 2020). "POFUT1 immunohistochemical staining was predominantly observed in the cytoplasm of epithelial cells, the staining showed gradual increase of POFUT1 expression through different stages of colorectal tumor progression, thereby verifying the molecular profiling data." (PMID 31411736, 2020).
esophageal squamous cell carcinoma (2 papers, 2023 to 2025). Esophageal squamous cell carcinoma (ESCC) is a type of esophageal carcinoma (EC) that can affect any part of the esophagus, but is usually located in the upper or middle third. "POFUT1 may also serve as an early biomarker in esophageal squamous cell carcinoma (ESCC) and non-small cell lung cancer (NSCLC), where POFUT1 is overexpressed in tumor tissues and promotes cancer progression." (PMID 40773107, 2025).
Hepatic fibrosis (2 papers, 2025). The presence of excessive fibrous connective tissue in the liver. "Experiments displayed that in the hepatic fibrosis mice model with POFUT1 knockout in LSECs, POFUT1 deficiency inhibited the KLF2-eNOS-sGC signaling axis, promoting injury-induced LSEC capillarization, while up-regulating the expression of fibrinogen in LSEC through the NOTCH/HES1/STAT3 pathway." (PMID 40761743, 2025). "These fibrinogens may foster HSCs activation by binding to integrin αvβ3/5 on HSCs’ membranes, suggesting the POFUT1/NOTCH/HES1/STAT3/fibrinogen axis as a novel therapeutic strategy of liver fibrosis." (PMID 40761743, 2025).
leukaemia (2 papers, 2016 to 2018). "We then analyzed the mRNA expression of POFUT1 in various leukemia cells line and found that this directly correlated with Notch-1 expression." (PMID 27233074, 2016).
mucinous adenocarcinoma (2 papers, 2018 to 2025). An invasive adenocarcinoma composed of malignant glandular cells which contain intracytoplasmic mucin. "POFUT1 overexpression is markedly associated with rectal location, non-mucinous adenocarcinoma and cancer stages IV and M1." (PMID 30380753, 2018). "In addition, POFUT1 is differently expressed according to histological type (p = 0.00001) with an overexpression in 75% of colon adenocarcinoma, 30.6% of colon mucinous adenocarcinoma, 88.4% of rectal adenocarcinoma and 46.2% of rectal mucinous adenocarcinoma." (PMID 30380753, 2018). "Overexpression of POFUT1 and NOTCH1 is preferentially observed in non-mucinous adenocarcinoma histological type." (PMID 30380753, 2018). "Interestingly, there is an inverse relationship between the expressions of POFUT1 and MUC2, a marker of mucinous adenocarcinoma (MAC), suggesting that POFUT1 influences tumor differentiation and progression specifically in the NMAC subtype." (PMID 40773107, 2025).
abortion (1 paper, 2020). the ending of pregnancy by removing a fetus or embryo before it can survive outside the uterus. "Serum levels of epiregulin and poFUT1 were higher in pregnant women compared with non‐pregnant women, and their levels were significantly decreased in abortion patients compared with pregnant women." (PMID 31889361, 2020). "Western blot also showed that epiregulin and poFUT1 levels were higher in the pregnant women than in the abortion patients." (PMID 31889361, 2020). "We compared the expression of epiregulin and poFUT1 in the villi of pregnant women and abortion patients." (PMID 31889361, 2020). "Immunofluorescence staining showed that epiregulin and poFUT1 were localized in villous trophoblast cells, and both stainings were stronger in normal pregnant women than in abortion patients." (PMID 31889361, 2020). "It was worth noting that there was a positive correlation between the epiregulin and poFUT1 expression levels in the serum of pregnant women (r = .9710) and abortion patients (r = .9237)." (PMID 31889361, 2020). "In the present study, the serum level of epiregulin and poFUT1 in pregnancy women and abortion patients were examined, and the decreased levels of epiregulin and poFUT1 were associated with abortion." (PMID 31889361, 2020). "As shown by ELISA, the levels of epiregulin, poFUT1 and uPA were decreased in the serum of abortion patients compared with pregnant women." (PMID 31889361, 2020).
alopecia (1 paper, 2011). Hair loss usually from the scalp. "In contrast, Pofut1/Tgfb3-Cre mice had an average life span of 4–5 months and exhibited progressive alopecia in a head-to-tail direction after 3 weeks postpartum." (PMID 21267458, 2011). "Since Pofut1/Tgfb3-Cre mice displayed alopecia at the second hair cycle, we undertook a histological analysis on control and mutant mice at different stages of the hair cycle." (PMID 21267458, 2011).
atopic dermatitis (1 paper, 2011). "Interestingly, Pofut1/Tgfb3-Cre mice displayed splenomegaly and lymphoadenopathy around 3 weeks of age and developed full-blown atopic dermatitis-like disease in adult (data not shown)." (PMID 21267458, 2011).
bladder cancer (1 paper, 2022). "For instance, low expressions of glycosyltransferase genes B4GALT1, EXT1, MGAT5B and POFUT1 predicted poor patient’s survival in bladder cancer." (PMID 36110252, 2022).
chromophobe kidney carcinoma (1 paper, 2018). "COAD (colon adenocarcinoma) and READ (rectum adenocarcinoma) presented the greatest means of log2 RSEM (RNA-Seq by Expectation Maximization) 11.633 and 11.962, respectively for POFUT1, only being exceeded in chromophobe kidney carcinoma KICH (12.086)." (PMID 30380753, 2018).
colorectal adenocarcinoma (1 paper, 2017). The most common type of colorectal carcinoma. "For the convenience of calculations and comparable statistic results, the co-expression data between all genes (20436) and STAU1 and POFUT1 in CRC was downloaded from The cBioPortal for Cancer Genomics (Colorectal Adenocarcinoma (TCGA, Provisional) 633 samples)." (PMID 29108255, 2017).
glioma (1 paper, 2023). A benign or malignant brain and spinal cord tumor that arises from glial cells (astrocytes, oligodendrocytes, ependymal cells). "In detail, STT3A and POFUT1 demonstrated the highest correlation degree (R = 0.84), which might demonstrate the synergistic effects of both genes to promote glioma malignant behaviors." (PMID 37663248, 2023).
head and neck squamous cell carcinoma (1 paper, 2025). A squamous cell carcinoma that arises from any of the following anatomic sites: lip and oral cavity, nasal cavity, paranasal sinuses, pharynx, larynx, and salivary glands. "Similarly, in head and neck squamous cell carcinoma, POFUT1 overexpression is associated with perineural invasion (PNI), where increased N-cadherin and vimentin and decreased E-cadherin levels support the EMT-driven invasive phenotype." (PMID 40773107, 2025).
heart failure (1 paper, 2017). Inability of the heart to pump blood at an adequate rate to meet tissue metabolic requirements. "POFUT1 inactivation disrupts signaling events and results in excessive angiogenic cell proliferation and plexus formation, leading to anomalous coronary arteries, myocardial infarction and heart failure." (PMID 28924218, 2017).
ischemic heart disease (1 paper, 2017). "Disruption of Pofut1 in ventricular endocardium results in structural coronary artery anomalies and early-onset ischemic heart disease due to insufficient coronary oxygen perfusion." (PMID 28924218, 2017). "Disruption of Pofut1, which controls the strength of NOTCH ligand binding, or Dll4, results in coronary artery anomalies that lead to early-onset ischemic heart disease." (PMID 28924218, 2017).
liver disease (1 paper, 2025). "Lastly, conditional knockout of Pofut1 in mouse endothelial cells facilitated liver injury-induced fibrosis, which is noteworthy given a single patient described with liver disease due to homozygous mutation of POFUT1." (PMID 40725456, 2025). "A single patient harboring a homozygous mutation in POFUT1 is described as also having global developmental delay, microcephaly, and liver disease." (PMID 40725456, 2025).
microcephaly (1 paper, 2024). A congenital or acquired developmental disorder in which the circumference of the head is smaller than normal for the person's age and sex. "Two other ER enzymes have been directly linked to microcephaly: POFUT1 and MINPP1." (PMID 39115595, 2024).
myocardial infarction (1 paper, 2017). Gross necrosis of the myocardium, as a result of interruption of the blood supply to the area, as in coronary thrombosis. "Histologically, Pofut1;Vegfr2DKO mice had no sign of myocardial infarction by HE staining, nor was there increased cardiac fibrosis by Sirius Red staining." (PMID 28924218, 2017).
oral cancer (1 paper, 2018). "POFUT1 is predominantly overexpressed in colorectal metastasis (83.9%) and could O-fucosylate other protein targets than NOTCH receptors, such as AGRIN which was shown to enhance tumor progression by activating cell migration and invasion in oral cancer." (PMID 30380753, 2018).
ovarian carcinoma (1 paper, 2026). A malignant neoplasm originating from the surface ovarian epithelium. "Western blot analysis confirmed POFUT1 protein upregulations in prostate and ovarian cancer cell lines (1.7-2.1-fold." (PMID 42122137, 2026).
rectal cancer (1 paper, 2017). A primary or metastatic malignant neoplasm that affects the rectum. "Furthermore these microRNAs can directlay target PLAGL2 and POFUT1 and repress the expression of both genes in colon and rectal cancer." (PMID 29108255, 2017). "The results showed that E2F4 and SP3 correlated significantly with POFUT1 and PLAGL2 in colon and rectal cancer, which indicated E2F4 and SP3 are the most likely transcription factor binding to this bidirectional promoter and causing co-expression of the gene pair." (PMID 29108255, 2017).
cancer (22 papers, 2017 to 2026). A tumor composed of atypical neoplastic, often pleomorphic cells that invade other tissues. "In both cancer types, potential diagnostic biomarkers linked to POFUT1 were found in the patient bloodstream." (PMID 40773107, 2025). "The quantity of pro-apoptotic markers, such as cleaved caspase-3 (CASP3) and Bcl2-associated X protein (BAX), is increased in POFUT1-silenced cancer cells, while anti-apoptotic proteins like BCL2 decreased." (PMID 40773107, 2025). "Patients with low POFUT1 mRNA expression showed a 4.4-fold greater risk of a shortened lifespan regarding cancer-specific survival (CSS), compared to those with higher expression levels." (PMID 40773107, 2025). "In contrast, low POFUT1 mRNA expression is associated with a higher risk of overall and cancer-specific death in muscle-invasive bladder cancer (MIBC) treated with radical cystectomy." (PMID 35335147, 2022). "Abnormal NOTCH signaling has been associated with human POFUT1 dysfunction in various cancers such as breast, hepatocellular or colorectal ones where POFUT1 overexpression is correlated with tumor development." (PMID 31500188, 2019). "During cancer development, though a role has been implicated in solid cancers, the contribution of POFUT1 to CRC was less well understood." (PMID 30250219, 2018). "Additionally, high POFUT1 expression and high risk of progression to cancer were associated with a decrease in goblet cell differentiation." (PMID 31411736, 2020). "A high POFUT1 expression correlated with poor overall survival in eight cancer types (HR range: 1.8-3.2, p < 0.01) and disease-free survival in seven cancers." (PMID 42122137, 2026). "POFUT1 has been shown to significantly enhance the migration and invasion abilities of cancer cells." (PMID 40773107, 2025). "The dysregulation of POFUT1 has profound effects on multiple signaling pathways critical to cancer development." (PMID 40773107, 2025). "It supports the notion that POFUT1 is a cancer driver participant, acting on its progression and on cancerous cellular survival, synergistically with other impaired oncogenes and/or tumor suppressor genes." (PMID 40773107, 2025). "This review provides a comprehensive analysis of the molecular and cellular consequences of POFUT1 dysfunction in cancer." (PMID 40773107, 2025). "POFUT1 has been shown to stabilize PD-L1 on the surface of cancer cells by preventing its ubiquitination and subsequent degradation." (PMID 40773107, 2025). "These experimental findings highlight the significant impact of POFUT1 on cancer cell proliferation, migration, invasion, and apoptosis." (PMID 40773107, 2025). "It drives a more aggressive cancer phenotype, emphasizing the critical role of POFUT1 in tumor progression through vascular mechanisms." (PMID 40773107, 2025). "Although POFUT1 consistently contributes to tumor malignancy, its specific impacts on tumor progression vary depending on the type of cancer." (PMID 40773107, 2025). "POFUT1 dysregulation enhances Notch signaling in various cancers, where its overexpression leads to higher NICD levels and increased transcriptional activity of Notch target genes." (PMID 40773107, 2025). "Although the role of POFUT1 in cancer progression has drawn significant interest due to its involvement in regulating key cellular processes, the precise mechanisms by which POFUT1 contributes to tumor progression remain incompletely understood." (PMID 40773107, 2025). "In numerous cancers, the expression of POFUT1 is very largely upregulated, often leading to an increased quantity of the enzyme." (PMID 40773107, 2025). "Such considerations underscore the complexity of POFUT1’s role in cancer and highlight the need for cancer-specific therapeutic strategies." (PMID 40773107, 2025). "MIBC patients with decreased POFUT1 mRNA levels showed poor outcomes for overall survival, cancer-specific survival, and disease-free survival." (PMID 35335147, 2022).